CD163 (CD163 molecule)
Diseases named in the same sentence as CD163 in open-access papers (continued):
Sharing a sentence is not in itself a finding about the gene and the disease.
tumor (continued). "The results showed a positive correlation between TYMP and CD163 gene expression, both in macro- and microdissected tumor tissue." (PMID 35567733, 2022). "The number of CD8+, FOXP3+, CD68+, CD163+ and PMNs was highly variable, however, all immune cells prevailed in stroma when compared to tumor nests." (PMID 35681497, 2022). "DRS measurements were correlated to end-point immunohistochemistry (IHC) markers of hypoxia (carbonic anhydrase-9) and microvasculature (CD31), along with tumor-associated macrophage recruitment (CD68) and M2 tumor-associated macrophage recruitment (CD163)." (PMID 35461243, 2022). "This indeed seems to be the case, as the characteristics of the tumor stroma (fibroblasts and CD163-positive immune cells) are remarkably different between MRI false-negative and MRI true-positive lesions." (PMID 36874403, 2022). "M1 macrophages are immunostimulatory and anti-tumoral, while M2 macrophages, characterized by the expression of CD163, enhance tumor progression and support metastasis." (PMID 35204426, 2022). "POSTN is also expressed in the cancer stroma of DFSP almost exclusively in the proximity of tumor nodules and restricted to the mesenchymal side, where CD163+ TAMs and MMP-producing cells are abundant." (PMID 35409404, 2022). "In general, higher levels of CD163+ TAMs compared to CD68+ are detected across all TET subtypes, while CD163+ population also exhibits a progressive enrichment along with the aggravation of tumor malignancy." (PMID 35887212, 2022). "The depletion of CD163+ TAMs correlated with an increase in tumor-infiltrating lymphocytes and when T cells were depleted, the effect on tumor growth restriction was reversed." (PMID 36211808, 2022). "Meanwhile, CD163+ TAMs are also known to be associated with epithelial–mesenchymal transition (EMT), the mesenchymal circulating tumor cell ratio, and a poor prognosis of CRC, in accordance with this present study." (PMID 36551651, 2022). "In contrast to other tumor types (gastric cancer, lung adenocarcinoma), the presence of CD163-positive M2-polarized macrophages is necessary to inhibit the progression of OS." (PMID 36297616, 2022). "Meanwhile, Tumor associated macrophages shifted towards anti-tumor M1-like subtypes, with CD68+CD163+ M2-like subpopulation significantly decreased (P = 0.04)." (PMID 36686751, 2022). "Since CD163+ macrophages in the tumor‐adjacent normal‐like epithelium were the strongest prognostic factor for outcomes above, 2 of these 6 biopsies were taken from the tumoral zones and 4 from the adjacent sextants based on preoperative biopsy parameters." (PMID 35075795, 2022). "CD8+ T cells appeared in closer proximity to tumor cells, CD163+ macrophages and FoxP3+ cells in HPV-positive primary tumors, and related metastases." (PMID 36123711, 2022). "CD163+ macrophages were more abundant within the tumor area and at the edge of brain metastases (P = 0.0044 and 0.0028, respectively)." (PMID 35316217, 2022). "Our results indicate a significant increased number of both CD68+ and CD163+ cells in the center of the GBM tumor with respect to the outside." (PMID 36611806, 2022). "Tumor-associated macrophages represent a major part of the leukocyte infiltrate in the TME, where the dominant phenotype is CD163+ M2 macrophages with tumor-promoting functions." (PMID 35204426, 2022). "CD206 is a marker of glutamine metabolism, CD163 is a marker of iron metabolism, and ARG1 is associated with tumor-derived lactic acid." (PMID 35350571, 2022). "THE high infiltration of CD163 was significantly different in tumor, paratumor and normal tissues of RCC, P<0.05." (PMID 35936748, 2022). "Using CyCIF data, we found that CD73 expression in tumor cells was spatially correlated with CD163 and CD11b expression in PU.1-positive myeloid cells." (PMID 35973991, 2022). "Positive correlation was also found between ZEB1 and TIM-3, as well as CD8 and the following markers: PD-1, PD-L1+ tumour cells, CD163, and LAG-3." (PMID 36358805, 2022).
tumor (continued). "In this study, we found that macrophages enriched in tumor tissue exhibited high expression of CD163 and CD68 (M2-like macrophages)." (PMID 35812401, 2022). "It has been reported that intrapleural infusion of TMPs-MTX significantly decreased the numbers of tumor cells and CD163+ macrophages in the pleural immune microenvironment." (PMID 36275698, 2022). "We should also note the differences in the content of PU.1+and CD163+ cells, depending on tumor localization." (PMID 36694901, 2022). "Macrophages present in the tumor microenvironment are called tumor-associated macrophages (TAM), and they are characterized by the expression of CD163, a highly specific monocyte/macrophage marker for polarized M2 macrophages." (PMID 35055124, 2022). "Based on these findings, we further examined multiplexed immunofluorescence using the antibodies for CD8, CD163, PD-1, PD-L1, and cytokeratin (CK) to characterize the immune microenvironment of the tumor." (PMID 35022193, 2022). "Consistently, PTX3 was more co‐expressed with CD68 and CD163 in tumor tissues than in paratumor tissues." (PMID 35855654, 2022). "It is reported ovarian cancer cells polarize macrophages toward an M2 phenotype in vivo which gradually gain expression of M2-like marker genes, such as CD206, Arg1, and CD163, at 4–8 weeks after tumor injection." (PMID 36035994, 2022). "In hypoxic zones, breast cancer cells produce Oncostatin M (OSM) that induces macrophage polarization toward a tumor-promoting phenotype (higher expression of CD163, CD206, Arg1 and Cox-2)." (PMID 35309358, 2022). "The abnormalities of CD8 cells and CD163 cells in the tumor microenvironment are related to the progression of PTC." (PMID 35185791, 2022). "A study of 148 tumor tissue samples revealed that highCD68+/CD163+ infiltration was a marker of unfavorable prognosis." (PMID 36694901, 2022). "Tumor-associated macrophages (TAMs), which play a role in the development of various tumor entities, are similar to M2 macrophages and express the macrophage antigen CD163." (PMID 36139588, 2022). "Instead, we found a tendency towards higher absolute macrophage infiltration (for both CD68+ and CD163+ cells) in the tumor core compared to the infiltration zone." (PMID 34654395, 2021). "The amount of CD163-positive (“M2”) macrophages increased both in the tumor and non-tumor compartment following dinutuximab, whereas the density of cytotoxic T cells remained stable at a low level." (PMID 33572900, 2021). "The M2-like phenotype (CD163 + Iba1+) microglia/Mφ in the tumor control (71%) and Lipo-DOX–2 (81.6%) mice displayed a higher distribution ratio than the dLGG–10 mice (27.7%) and dLGG–10 + Lipo-DOX–2 (31%) mice." (PMID 34439274, 2021). "In our spontaneous KP tumours, we observed increased expression of the M2 marker, CD163, relative to the transplanted tumours, although the significance of this observation was not further assessed in this study." (PMID 34242269, 2021). "As expected, the expression of the M2 markers CD206 and CD163 correlated with the stage, as their mRNA level in TAMs is higher in more advanced tumor samples." (PMID 34260142, 2021). "Together, these observations indicate that tumor cell nest-specific colocalization of PD-1+ helper T cells and CD163+ TAM reflects a tumor-promoting microenvironment and disease aggressiveness." (PMID 34777389, 2021). "Immunofluorescence showed that the proportion of CD68+ and CD163+ double-positive cells (M2 macrophages) infiltrating the tumor tissue of the experimental group was significantly higher than that in the control group." (PMID 34093541, 2021). "CD68+ cells were found to be clustered with tumor cells and dispersed from stromal cells, while CD163+ and CD206+ cells were found to be clustered with stromal cells and dispersed from tumor cells." (PMID 33882057, 2021).
tumor (continued). "Upon further characterizing this subset of cells during early tumor formation using CD163 as a marker for M2-subset macrophages, there was distinct infiltration of lung tumors in Kras transgenic mice (right)." (PMID 34715561, 2021). "Immunohistochemistry analysis performed in the resected injected tumors revealed extensive tumor necrosis, cellular debris, and tumor infiltration with immunosuppressive macrophages (with increased CD163/CD68 ratio) on the edges of tumor plane." (PMID 34662233, 2021). "We analyzed the absolute count and percentage of CD45+ leucocyte, CD68+ macrophage and CD163+ M2 type macrophages in the tumor core, perivascular area and tumor infiltration zone." (PMID 34654395, 2021). "There was a strong positive correlation between the infiltration of CD20+ B lymphocytes and other immune profiles (i.e., CD4+, CD8+, and FOXP3+ TILs, and CD68+ and CD163+ macrophages) both in stroma and tumor nests." (PMID 33494389, 2021). "Silencing CD163 abrogated macrophage-induced tumor cell proliferation in co-cultured cells of human monocyte-derived macrophages and leiomyosarcoma and myxofibrosarcoma cell lines." (PMID 33763066, 2021). "A visible number of tumor-associated myeloid cells including CD68+ and CD163+ macrophages and CD33+ myeloid cells were also detected in most tumor tissues." (PMID 34257571, 2021). "CD163+ tumor-associated macrophages (TAM) provided the strongest correlation with PD-1+ helper T cells, and cases with a high density of PD-1+ helper T cells and CD163+ TAM had a significantly shorter overall survival than other cases." (PMID 34777389, 2021). "According to CD86/CD163 ratio and tumor stage, stage II-III patients were stratified into four recurrence-risk subgroups (high-ratio stage II, high-ratio stage III, low-ratio stage II, and low-ratio stage III)." (PMID 34512652, 2021). "Monocytic-lineage cells from IDH-A specimens over-expressed markers of a tumor-supportive phenotype (e.g., CD163), compared to IDH-O specimens." (PMID 34763709, 2021). "In this study, we found an association between clinical benefit from ipilimumab therapy and the coexistence of low densities of CD8+ and high densities of CD163+ PD-L1+ cells at the periphery of the tumor." (PMID 34066146, 2021). "As M2 macrophages, unlike M1 macrophages, are recognized to be tumor supporting, we utilized the M2 markers CD204 and CD163 to investigate the presence of M2 macrophages in the GBM tumor microenvironment." (PMID 34572134, 2021). "Clinically, NSCLC patients with increased intratumoral Rab37+IL-6+ immune cells where enriched with tumor infiltrated CD163+ M2-TAMs and exhausted PD-1+CD8+ T cells show poor prognosis." (PMID 34093869, 2021). "A spatial immunological exclusion of CD8+ T lymphocytes and CD163+ macrophages outside the tumor areas was found after anti-PD-1 in this patient #1." (PMID 34771650, 2021). "CRCs contained various numbers of tumor-associated immune cells (TAIs) with SIRPA, CD68, or CD163 expression." (PMID 33799989, 2021). "Some cases of spontaneous MPM regression likely related to an activation of the immune system have been reported and a worse outcome has been related with high CD163+ tumor-associated macrophages and low CD8+ tumor infiltrating lymphocytes." (PMID 36046087, 2021). "The crosstalk between PLXDC2 expressed tumor stroma and CD163 macrophages and with tumor cell’s EMT process is extricate and interesting." (PMID 34124056, 2021). "In this study, we evaluated the infiltration of macrophages marked with CD86 and CD163 in tumor tissues by the immunohistochemistry technique and focused on CD86/CD163 ratio, according to the STROBE guidelines." (PMID 34512652, 2021). "This was associated with significant reductions in tumor associated FOXP3+ cellular infiltration and CD163+ M2-type macrophage infiltration." (PMID 34715561, 2021).
tumor (continued). "We provide the evidence that the monocyte subpopulation marked by CD163 and the whole transcriptome of circulating monocytes is affected by the presence of tumor." (PMID 35237501, 2021). "IHC shows that CD68 is expressed either in the tumor or the stroma compartment, and exhibits amoeboid or ramified morphology, whereas CD163+ cells display ramified morphology in the same localizations." (PMID 34200100, 2021). "Depletion of these CD163+ cells resulted in increased infiltration of iTAMs which had an inflammatory phenotype and subsequently activated T cells were attracted to promote tumor regression." (PMID 33572437, 2021). "In contrast, densities of tumor-infiltrating CD163+ macrophages/monocyte were weakly (r = 0.19, p = 0.04) associated with only one of the top ten ICH genes (CCR5)." (PMID 34454518, 2021). "An increased CD163+/CD68+ ratio in the tumor invasive front (TF) was positively correlated with shorter RFS and OS rates in CRC." (PMID 34445193, 2021). "PD-L1 expression (≥1%) in the tumor and CD163 expression in paracancerous stroma appeared positively correlated with tumor shrinkage during the neoadjuvant treatment phase." (PMID 35095878, 2021). "While the expression of CD163 in tumor cells is a marker of poor prognosis, high CHID1 expression is a marker of favorable prognosis." (PMID 33466316, 2021). "Tumor-infiltrating macrophages (TIMs) (CD163+ (M2) and CD68+ (M1)) play a key role in the tumor microenvironment." (PMID 34207243, 2021). "CD163 + M2 macrophages constitute 45% (NE-low) and 22% (NE-high) of the immune cell pool in tumor nests." (PMID 34200100, 2021). "PD-L1、B7-H4、FOXP3 and CD163 protein expression in tumor tissues were detected by immunohistochemistry." (PMID 34307135, 2021). "Inconsistent expression of PD-L1 and CD163 protein were detected in tumor and paracancerous stroma, respectively." (PMID 35095878, 2021). "In the areas of tumor perivascular cuffing, CD163+ single cells were the dominant immune population." (PMID 34691054, 2021). "The current study was extended to investigate the correlation between MACC1 expression and CD163+ tumor-associated macrophages, CD56+ natural killer cells, and CD8+ cytotoxic T lymphocytes within BC tumor microenvironment." (PMID 34577857, 2021). "We found an increase in CD163+ macrophages in the tumour periphery compared to the tumour core, suggesting increased macrophage recruitment." (PMID 34290237, 2021). "The expression of four CAF-specific markers correlated positively with that of CD68, CD163, MRC1, IL10, and TGFB1, which are markers that characterize tumor-associated macrophages (TAMs)." (PMID 33799788, 2021). "An integrated gene profile and functional analysis of the proportions of tumor-infiltrating immune cells revealed that the expression of the M2 macrophages cell marker CD163 was positively correlated with PLXDC2 expression." (PMID 34124056, 2021). "These tumor-infiltrating TAM are skewed toward CD163+ M2 phenotype under the action of the transcription factor, GATA3, and cytokines, including IL-4, IL-6, and IL-13, and promoted an immunosuppressive TME in EAC." (PMID 33995371, 2021). "For the first time, we clearly show that CD68−/CD163+ macrophage dominate in OM tumor regions, over other macrophage phenotypes." (PMID 33498676, 2021). "We also analyzed the M2-like phenotype of TAMs by detecting CD206-positive cells in spleens and CD206/CD163/CD86/CD80-positive cells in tumor tissues." (PMID 33537094, 2021). "High CCL2 level also correlated with high CD68 and CD163 staining in tumor tissues, supporting the role of CCL2 in TAM recruitment." (PMID 34572939, 2021). "A total of 335 patients who had undergone surgery for stage I–IIIA NSCLC were enrolled into this analysis and assessed for CD66b(+) neutrophils and CD163(+) macrophages in tumor nests and the adjacent stroma by means of immunohistochemistry." (PMID 34885082, 2021).
tumor (continued). "Specific depletion of CD163+ macrophages results in massive infiltration of activated T cells and tumor regression." (PMID 33968055, 2021). "We divided NPC patients into three subgroups based on EBV and HPV status (EBV−/HPV-, EBV+/HPV-, EBV+/HPV+) and investigated MIF, CD11c, CD68, and CD163 IF scores in tumor nest and tumor stroma." (PMID 34407796, 2021). "Pooled analysis of studies investigating the association between CD163 and prognosis found that patients with increased tumour infiltration by CD163 macrophages had shorter OS in PDAC." (PMID 33481339, 2021). "We also assessed the infiltration of CD163+ macrophages in primary tumours overexpressing IL-1B in IL-1Bfl/fl and IL-1B−/− mice." (PMID 34290237, 2021). "The results showed that the proportion of CD45+CD14+CD163+ mono-macrophage subset infiltrated by tumor tissue was significantly higher than that in paracarcinoma tissues." (PMID 34803459, 2021). "Another crucial finding shows that most CD68 + TAMs are M2-polarised, and express CD163 in NE-low tumor subsets, creating an immunosuppressive microenvironment peculiarly inside tumor nests." (PMID 34200100, 2021). "Among the CD45+ cell population, tumor-associated macrophages (TAM) were further investigated using two markers F4/80 and CD163." (PMID 34689156, 2021). "Tumor cell-derived FGD5-AS1 via exosomes transportation promotes upregulation of M2 polarization markers (CD163, CD206, ARG1) and downregulation of M1 macrophage markers iNOS and IL-2 in NSCLC." (PMID 35047506, 2021). "Further immunostaining revealed many CD163‐positive tumor‐associated macrophages (TAMs), CD15, myeloperoxidase (MPO)‐positive tumor‐associated neutrophils (TANs), and CD3, CD25‐positive regulatory T cells (Tregs) in the tumor." (PMID 33174378, 2021). "The density of CD14+, CD68+, CD163+ cells in the intratumoral tumor (IT Tumor) compartment was significantly higher in hrHPV+ tumors than in hrHPV− tumors (p < 0.001, p < 0.001, p < 0.001, respectively)." (PMID 34194435, 2021). "GBM stood out as having the highest CD163/CD3E ratio of the 30 tumor types analyzed, indicating GBM tumors have a uniquely TAM-dominated TIME combined with poor T cell infiltration." (PMID 34083417, 2021). "TAMs can be grouped in two major categories: 1) CD163- M1 macrophages, which are pro-inflammatory and 2) CD163+ M2 macrophages that are anti-inflammatory and are preferentially recruited at the tumor site." (PMID 35071240, 2021). "In patients who had an MRI diagnosis of residual tumor, most of the peripheral monocytes that in the preoperative stage were CD163+ FKBP51s− had turned into CD163+ FKBP51s+." (PMID 33917598, 2021). "IL-1B ablation in the microenvironment removed this spatial bias, resulting in an equal number of iNOS+ and CD163+ macrophages in both areas of tumour viability and necrosis." (PMID 34290237, 2021). "The levels of the second M2 population (CD68+CD163+) were similar in both groups (p = 0.1869 for tumor parenchyma and p = 0.7626 for stroma)." (PMID 33807310, 2021). "In melanoma, the depletion of CD163+ MΦs promotes tumor infiltration by activated T lymphocytes and tumor regression." (PMID 34771453, 2021). "We found that blastemal tumor areas were almost devoid of CD163 positive M2 type macrophages, while tumor areas with stromal differentiation showed dense macrophage infiltrates and areas displaying epithelial differentiation showing an intermediate density." (PMID 33670534, 2021). "We found that several pro-tumor markers are increased in cancer tissues, including CD163, CD206, SIRPα, LILRB1, SIGLEC10, AXL, MERTK, and MARCO." (PMID 34778091, 2021). "Particularly, a decreased CD8+ T cell population and an increase in F4/80+ CD163+ M2 macrophages were found in the tumor microenvironment of the H22OE group." (PMID 34838121, 2021).